ALB (albumin)
Diseases named in the same sentence as ALB in open-access papers (continued):
Sharing a sentence is not in itself a finding about the gene and the disease.
Hypercholesterolemia (47 papers, 2009 to 2025). An increased concentration of cholesterol in the blood. "Albuminuria, which is defined as urinary albumin excretion exceeding 30 mg of albumin/g of creatinine, has been found to be associated with hypercholesterolemia." (PMID 38791535, 2024). "Taken together, we propose that ZWT could ameliorate the proteinuria, low serum albumin, hypercholesterolemia, and loss of kidney function of NS rats." (PMID 24812565, 2014). "According to this hypothesis, analbuminemic rats show hypercholesterolemia, and patients with congenital albumin deficiency show elevated serum cholesterol and phospholipid concentrations, which temporarily return to normal after intravenous albumin infusion." (PMID 34638659, 2021). "Clinically, analbuminemia is characterized by very low plasma albumin, hypotension, and severe hypercholesterolemia but normal triglycerides and HDL-cholesterol." (PMID 40004987, 2025). "ALB: A very rare cause of severe hypercholesterolemia is analbuminemia, an autosomal recessive disease due to genetic loss of the ALB gene that encodes for albumin." (PMID 40004987, 2025). "Hypercholesterolemia was observed only in mice with particularly severe proteinuria (ACR > 15 mg albumin/mg creatinine)." (PMID 34341345, 2021). "The mean values of serum albumin, total energy intake, and protein- and fat-energy ratio and the frequencies of living alone and hypercholesterolemia were significantly higher in participants at the survey in 2017 than those at the survey in 2012." (PMID 32507775, 2021). "The biochemical analysis of liver function markers has shown that continuous feeding of RHMVO induced hypercholesterolemia, which resulted in significantly (p < 0.005) reduced total protein and albumin levels." (PMID 32664977, 2020). "Hypercholesterolaemia was present in 58 (10.8%) and a high spot random urine albumin : creatinine ratio in 5 (1.0%)." (PMID 30057806, 2018). "The present study was an attempt to develop galactosylated albumin nanoparticles of Simvastatin for treatment of hypercholesterolemia." (PMID 25901147, 2015). "Marked proteinuria due to NS causes severe hypoalbuminemia, promotes lipoprotein synthesis, and induces excessive albumin synthesis, resulting in hypercholesterolemia." (PMID 24535024, 2014). "A single TA1m treatment raised serum albumin levels in diabetic rats to normal and significantly reduced hypertriglyceridemia and hypercholesterolemia." (PMID 23826312, 2013). "Moreover, in HD group the differences in RNLS levels between genotypes didn’t change statistically after adjustment for potentially confounding effect of age, sex, BMI, albumin and hemoglobin level, the presence of hypercholesterolemia and residual diuresis." (PMID 28372594, 2017). "Further laboratory investigations disclosed hypercholesterolemia (total fasting cholesterol 320 mg/dL, desirable <200 mg/dL), hypertriglyceridemia (fasting triglycerides 576 mg/dL, reference range <150 mg/dL), and plasma albumin levels of 2.9 g/dL (reference range 3.4 to 5.4 g/dL)." (PMID 38790019, 2024). "This study aimed to design a novel oral formulation of bovine albumin serum nanoparticles (BSA NPs) loaded with an extract of Eisenia bicyclis and to validate its beneficial health effects, particularly targeting hypercholesterolemia and CVD prevention." (PMID 36286431, 2022). "The increased albumin excretion observed in the HC‐diet‐fed rats, along with simultaneous elusive changes in the excretion of oxidative stress markers, suggests that albuminuria may be taken as an early marker of glomerular dysfunction accompanying hypercholesterolemia." (PMID 34110719, 2021). "Moreover, correlation analysis indicated that C3 correlated positively with serum cholesterol and DD and negatively with total protein and albumin, suggesting that renal tubular C3 deposition may aggravate hypercholesterolemia, hypercoagulability, and hypoproteinemia." (PMID 30003098, 2018).
Hypercholesterolemia (continued). "Urinary excretion of protein >3.5 g/day, together with serum albumin at 3 g/day or less or serum total protein level of 6 g/day or less (these are essential diagnostic conditions), is expected to be maintained in association with edema and hypercholesterolemia (not essential items)." (PMID 24535024, 2014). "In conclusion, hypercholesterolemia may adversely affect renal function through oxidatively modified LDL, which interferes with the renal handling of albumin and leads to the development of albuminuria." (PMID 38791535, 2024). "Laboratory results showed elevated AFP 23.1 ng/mL (normal range < 15 ng/mL) and normal albumin of 4.61 g/dL (normal range: 3.5–5.5 g/dL), without hypercholesterolemia." (PMID 35203940, 2022). "In the present study, we showed that the high cholesterol diet increased albumin content within the hippocampal tissue of aged mice, but not young mice, suggesting a synergic effect of hypercholesterolemia and aging on increased permeability of the BBB." (PMID 29896426, 2018). "The severe hypercholesterolemia may be the result of a compensatory mechanism for the lack of ALB and provides evidence for the possible role of ALB in controlling lipoprotein metabolism." (PMID 31057599, 2019).
myocardial ischemia (47 papers, 2008 to 2025). A disorder of cardiac function caused by insufficient blood flow to the muscle tissue of the heart. "The IMA test is based on the fact that cardiac ischemia is associated with modifications in the structure of albumin and, thus, in the capacity of a specific binding site to bind cobalt." (PMID 38228668, 2024). "Ischemia-modified albumin level measurement has recently been proposed as an important diagnostic marker for myocardial ischemia." (PMID 39336570, 2024). "They play a role in mediating the physiological effects associated with cobalt toxicity and are central to the albumin cobalt binding (ACB) assay for diagnosis of myocardial ischemia." (PMID 37325156, 2023). "Albumin has been shown to suppress platelet activation and aggregation, whereas activated platelets can cause coronary artery contraction and worsen myocardial ischemia." (PMID 36712669, 2022). "Ischemia-modified albumin is considered a new biomarker for the assessment of myocardial ischemia that has early diagnostic value for myocardial ischemia." (PMID 32641068, 2020). "The frequency of microalbuminuria/ Moderate Albumin Excretion in treatment naïve type II diabetic patients was high and associated with the frequency of silent myocardial ischemia in treatment naïve type II diabetic patients with and without MAU MAU/MAE." (PMID 32292459, 2020). "The IMA test is based on the hypothesis that cardiac ischemia is associated with modifications of albumin structure which, in turn, decrease cobalt binding." (PMID 38228668, 2024). "Ischemia-modified albumin (IMA) has gained attention as a potential point-of-care diagnostic marker for detecting ischemic events, particularly myocardial ischemia." (PMID 39407566, 2024). "Ischemia-induced modification of human serum albumin (HSA) has been proposed as a serum biomarker of myocardial ischemia." (PMID 39925729, 2024). "Myocardial ischemia leads to formation of ischemia-modified albumin by cleavage of N-Asp-Ala- (namely, the first two N-aminoacid residues) of the albumin N-terminal." (PMID 37887045, 2023). "Ischemia-modified albumin (IMA) is an altered form of albumin that increases during myocardial ischemia." (PMID 37602073, 2023). "More recently, ischemia-modified albumin (IMA) has been used in the diagnosis of early myocardial ischemia and other ischemic diseases." (PMID 35663691, 2022). "Unlike RBP and β2-M, which reflect the function of renal tubules, IMA is a modification of albumin that is produced after myocardial ischemia." (PMID 35250538, 2022). "Hypothetically, the release of fatty acids in myocardial ischemia results in their binding to albumin, reducing albumin's ability to take up cobalt." (PMID 34336009, 2021). "MAU/MAE was determined by urinary albumin excretion rate of 30-300 mg/24 hours and included patients underwent exercise tolerance test to diagnose silent myocardial ischemia." (PMID 32292459, 2020). "Ischemia-modified albumin (IMA) is assumed “N-terminal modified” albumin which is generated immediately following myocardial ischemia." (PMID 28356609, 2017). "The myocardial ischemia generates “reversible” “ischemia-modified albumin, IMA” secondary to FA occupation of albumin, while the oxidative stress generates “irreversible” “oxidation modified albumin, OMA” secondary to oxidation adducts on albumin." (PMID 28356609, 2017). "Myocardial ischemia results in structural changes to the N-terminus of the serum albumin related to the production of ROS." (PMID 28698768, 2017). "It is important as one of biomarkers for early diagnosis of myocardial ischemia is “ischemia-modified albumin,” measured by the albumin-cobalt-binding assay." (PMID 26075218, 2015). "Ischemia Modified Albumin is a new marker used to detect myocardial ischemia and it shows an early change." (PMID 22221979, 2012).
myocardial ischemia (continued). "Treatment in the present study was initiated two days prior to myocardial ischemia as it was determined that albumin was maximally equilibrated with the heart after 48 hrs and consequently cardiac albiglutide exposure is greatest at this time (data not shown)." (PMID 21887274, 2011). "Free fatty acids unbound to albumin (FFAu) were also evaluated for early identification of cardiac ischemia." (PMID 19578525, 2008). "Ischemia-modified albumin (IMA) is a relativelynew biomarker in the identification of myocardial ischemia in advance or in theabsence of myocardial necrosis." (PMID 18483569, 2008). "This variant has a lower binding capacity to cobalt, and studies suggest that it may sensitively reflect myocardial ischemia (it can be measured by an albumin-cobalt binding assay)." (PMID 37762957, 2023). "Ischemia-modified albumin (IMA) is looked upon as a newer marker of myocardial ischemia." (PMID 36457615, 2022). "Myocardial ischemia affects albumin’s N-terminus, lowering cobalt’s capacity to bind to albumin." (PMID 35630031, 2022). "Ischemia-modified albumin was used as a marker of myocardial ischemia." (PMID 26330873, 2015). "Ischemia-modified albumin (IMA), a Food and Drug Administration-approved serum biomarker of cardiac ischemia and a risk stratification tool for suspected acute coronary syndrome, is produced during an ischemic condition or attack and is present in the blood in early and easily detectable levels." (PMID 22221979, 2012). "Ischemia-modified albumin (IMA) is a sensitive biomarker of cardiacischemia." (PMID 18483569, 2008). "Initially, the cobalt-binding capability of albumin was proposed for the assessment of IMA and demonstrated a high utility, mainly in myocardial ischemia." (PMID 38611583, 2024). "Ischemia-modified albumin (IMA) has emerged as a pivotal biomarker for the early detection of ischemic conditions, particularly myocardial ischemia, where timely diagnosis is crucial for effective intervention." (PMID 39407566, 2024). "A spectrophotometric test, the Albumin Cobalt Binding (ACB) test, has been developed to detect IMA and currently offers the possibility of improving the sensitivity of early diagnosis of myocardial ischemia (6–24 h earlier than troponin raise)." (PMID 36830061, 2023). "So-called “ischemia-modified albumin” (IMA) is found to be significantly elevated in ischemic patients, and serves as a biomarker for early detection of myocardial ischemia before the onset of irreversible cardiac injury." (PMID 30103926, 2018). "Ischemia-modified albumin (IMA) can be detected in the early stages of myocardial ischemia before the onset of myocardial necrosis, and is the first serum marker for myocardial ischemia to be approved by the United States Food and Drug Administration." (PMID 24223946, 2013). "The cobalt binding to albumin has been studied because the base of the “Albumin Cobalt Binding test” (ACB test) approved by the Food and Drug Administration for evaluating myocardial ischemia." (PMID 22084701, 2011). "Ischemia modified albumin (IMA), measured by the albumin cobalt binding test (ACB), has been shown to be a marker of myocardial ischemia." (PMID 19578525, 2008). "In this respect, ischemia-modified albumin (IMA), which is one of the serum biomarkers of tissue damage and myocardial ischemia, maybe a potential marker." (PMID 32232820, 2020). "Mothes and Faller speculated a putative relationship between FA binding to albumin site A and increased levels of free cobalt (i.e., increased IMA) in the ACB assay for patients with myocardial ischemia." (PMID 28356609, 2017). "HbA1c and U-albumin creatinine ratio were not significantly differently in patients with or without carotid arterial disease, PAD or myocardial ischemia, respectively." (PMID 21838881, 2011).
Anxiety (46 papers, 2013 to 2026). Intense feelings of nervousness, tension, or panic often arise in response to interpersonal stresses. "After the adjustments of sex, hemoglobin, urea nitrogen, total bilirubin, albumin and brain natriuretic peptide, the neutrophilic granulocyte percentage was significantly associated with anxiety (OR = 43.265, P = 0.012)." (PMID 36404328, 2022). "In addition, higher 0.1*age, lower albumin levels, and anxiety were independently associated with severe sleep disturbance in MHD patients." (PMID 35959399, 2022). "In addition, higher uric acid and BUN levels and a lower hemoglobin and serum albumin were also significantly associated with anxiety (p < 0.05)." (PMID 36612797, 2022). "Lower albumin levels have been previously associated with anxiety symptoms." (PMID 34831713, 2021). "In this present study, after the adjustments of sex, smoking index, hemoglobin, BUN, TBIL, albumin and BNP, the NEUT% was significantly associated with anxiety (OR = 43.265, P = 0.012)." (PMID 36404328, 2022). "In autumn, there were marked differences between groups in melancholic features, anxiety and pain, atypical features, uric acid, total bilirubin, conjugated bilirubin and albumin." (PMID 35463511, 2022). "After the adjustments of sex, smoking index, hemoglobin, BUN, TBIL, albumin and BNP, the NEUT% was significantly associated with anxiety (OR = 43.265, P = 0.012)." (PMID 36404328, 2022). "Patients with anxiety were less likely to be employed and to have had a previous kidney transplant and had lower serum albumin." (PMID 34831713, 2021). "The patients without anxiety showed higher hemoglobin, triglyceride, HDL-C, apolipoprotein A, albumin and LVEF while the patients with anxiety showed higher NEUT%, BUN, creatinine, TBIL, BNP and HAM-A14 score (P < 0.05)." (PMID 36404328, 2022). "By comparison, we found that patients with anxiety symptoms had elevated serum vitamin A, glycated serum protein, CRP, and aspartate aminotransferase as well as decreased serum total protein and albumin." (PMID 34007268, 2021). "The proportion of patients experiencing numbness was slightly higher in the anxiety group than that in the non-anxiety group (p = 0.049), and the albumin levels in the anxiety group were significantly lower than those in the non-anxiety group (p = 0.008)." (PMID 41169418, 2025). "Additionally, psychological and metabolic features were frequently selected across models, including Hamilton Anxiety Scale (HAMA) score, uric acid (UA), and albumin (ALB)." (PMID 41361301, 2025). "This group of patients showed less frequency of arteriovenous fistula as vascular access and slight decreases in hemoglobin, albumin and calcium serum levels compared to those patients without anxiety." (PMID 33805492, 2021). "However, albumin was not an independent factor for the presence of anxiety in our population, and other studies have actually reported that high albumin levels were associated with physical states of agitation or anxiety." (PMID 34831713, 2021). "Compared with patients without mental disorders, patients with anxiety symptoms showed elevated serum vitamin A, decreased total protein and albumin (P < 0.05), elevated glycated serum protein, increased CRP (P < 0.05), and increased aspartate aminotransferase (P < 0.001)." (PMID 34007268, 2021).